FGFR1 (fibroblast growth factor receptor 1)
Diseases named in the same sentence as FGFR1 in open-access papers (continued):
Sharing a sentence is not in itself a finding about the gene and the disease.
tauopathy (1 paper, 2021). Neurodegenerative disorders involving deposition of abnormal tau protein isoforms (tau proteins) in neurons and glial cells in the brain. "Problem 2 asked participants to predict compounds that bind the Tauopathy pro-targets AURKA, PAK1, FGFR1, and STK11 and avoid the Tauopathy anti-targets PAK3, MAP3K7, and PIK3CA." (PMID 34520464, 2021). "Problem 2 asked participants to predict compounds that bound the Tauopathy pro-targets, AURKA, PAK1, FGFR1, and STK11 and did not bind PAK3, MAP3K7, and PIK3CA." (PMID 34520464, 2021).
tendinopathy (1 paper, 2021). "Furthermore, gene variants of FOXP3, FCRL3, BMP4, and FGF3 and FGF10 as well as FGFR1 were analyzed in connection with tendinopathy in competitive athletes." (PMID 34366884, 2021).
testicular cancer (1 paper, 2020). A primary or metastatic malignant neoplasm that affects the testis. "In summary, cordycepin inhibited FGF9-induced testicular tumor growth by suppressing the ERK1/2, Rb/E2F1, cell cycle pathways, and the expressions of FGFR1-4 proteins, suggesting that cordycepin can be used as a novel anticancer drug for testicular cancers." (PMID 33172093, 2020).
Thrombocytopenia (1 paper, 2013). A reduction in the number of circulating thrombocytes. "Diminished expressions of PDGFB and VEGFR2, FGFR1, and FGFR2 were well correlated with the degree of thrombocytopenia in these cirrhotic patients (ρ>0.5, p<0.001)." (PMID 23620752, 2013). "These diminished expressions of PDGFB, VEGFR2, FGFR1, and FGFR2 were well correlated with the degree of thrombocytopenia in the cirrhotic patients." (PMID 23620752, 2013).
thyroid (1 paper, 2015). "In this study we investigated the expression of PKM2, LDHA and FGFR1 in thyroid benign and malignant tissues by employment of qPCR and western blot." (PMID 25880801, 2015).
tooth ankylosis (1 paper, 2024). Dental ankylosis is a rare disorder characterized by the fusion of the tooth to the bone, preventing both eruption and orthodontic movement. "Since Fgfr1 was also detected in the epithelium, we further tested whether loss of Fgfr1 in epithelial progenitor cells may cause tooth ankylosis by generating K14rtTA;teto-Cre;Fgfr1fl/fl mice." (PMID 38910207, 2024). "MicroCT analysis indicated that the apical root connected to the alveolar bone with narrowed PDL space and pulp cavity in Fgfr1 mutant mice, which is similar to tooth ankylosis." (PMID 38910207, 2024). "By PN60, in the Fgfr1 mutant mice the dental pulp cavity of the tooth root had narrowed significantly and the PDL in the apical root had almost disappeared, instead being filled with bone-like tissue connecting the root surface to the alveolar bone, which is a phenotype known as tooth ankylosis." (PMID 38910207, 2024).
type 1 Pfeiffer syndrome (1 paper, 2013). "FGFR1, the fibroblast growth factor receptor 1 plays an important role in facial morphogenesis, and mutations in this gene lead to syndomes associated with facial abnormality, such as the type 1 Pfeiffer syndrome (MIM 101600) and Kallmann syndrome 2 (KAL2) (MIM 147950)." (PMID 24339768, 2013).
tumor (815 papers, 2005 to 2026). "Collectively, these findings underscore the functional heterogeneity and tumor-specific roles of FGFR1 splice variants." (PMID 41584352, 2026). "As an example, the ratio of FGFR1 isoforms (FGFR1α and FGFR1β) is closely associated with cancer progression and prognosis, with FGFR1β being particularly linked to tumor initiation and poor survival outcomes in breast cancer." (PMID 41584352, 2026). "FGFR1 mutations at p.N546 were associated with high-risk disease and rapid tumor progression, resulting in dismal outcome for these patients." (PMID 41678281, 2026). "For instance, numerous preclinical studies are being conducted to evaluate targeting of tumor-associated factors, such as fibroblast growth factor receptor 1 protein (FGFR1), platelet-derived growth factor receptor alpha (PDGFRA), and VEGF receptor 2 (VEGFR2)." (PMID 41219972, 2025). "Tumor FGFR1–4 gene mutations are seldom isolated to a single mutation, and FGFRS gene mutations exhibit significant variations across different tumors, thus making clinical data collection challenging." (PMID 40860823, 2025). "In vivo, FGFR1 inhibition delays the growth of irradiated tumor xenografts, a process linked to reduced HIF-1α levels, without affecting blood vessel integrity." (PMID 41002392, 2025). "Targeted DNA NGS of the tumor tissue identified two FGFR1 mutations, c.1972A>C p.T658P and c.1968G>C p.K656N, both located within the FGFR1 kinase domain and representing the sole pathogenic mutations." (PMID 41323387, 2025). "Gatesman and colleagues similarly reported the discovery of a mosaic FGFR1 mutation from a single electrode inserted into known tumorous tissue in a male pediatric patient with a low-grade epilepsy-associated tumor (LEAT)." (PMID 40486667, 2025). "For instance, the spatial and temporal heterogeneity of actionable mutations in genes like ALK and FGFR1 can compromise the accurate assessment of a tumour’s susceptibility to targeted inhibitors." (PMID 41511287, 2025). "FGFR1 is closely associated with various types of cancers and has been extensively studied for anti‐tumor therapy." (PMID 39921455, 2025). "Remarkedly, the FGF/FGFR1/NOTCH1 within RB1 variant group has a dramatically higher inner‐tumor CD8+ T cell infiltration, following more CD8+PD‐1‐LAG3‐ non‐exhausted T cells and CD8+PD‐1+LAG3‐ exhausted T cells." (PMID 40001320, 2025). "N546K point mutation in FGFR1 gene is the most frequent FGFR1 gene alteration in cancer, and it was found in NB tumours as a clonal variant, suggesting its role as a driver mutation." (PMID 41511287, 2025). "Elevated FGFR1 levels have been linked to poor prognosis and increased tumor proliferation through MAPK pathway activation." (PMID 41315241, 2025). "The deregulation of FGFR1 signaling is associated with various human cancers, and targeted inhibitors of this pathway have proven successful in tumor therapy." (PMID 38790018, 2024). "Tumor recurrence or regrowth was observed in seven patients at a significantly higher rate for FGFR1 mutations (50.0%, 4/8) than BRAF V600E mutations (6.3%, 2/32; p = 0.048)." (PMID 39081340, 2024). "A study discovered that FGFR1/2 amplification or activating mutations were present in around 40% of circulating tumour DNA (ctDNA) after treatment with CDK4/6 inhibitors." (PMID 40135140, 2024). "Recent research has shown that IGFBP7 promotes the polarization of tumour‐associated macrophages (TAMs) via the FGF2/FGFR1/PI3K/AKT axis, thereby facilitating the progression of GC." (PMID 39351597, 2024). "Pathology was consistent with PA of the midbrain/pons and cerebellum, and molecular sequencing of the tumor revealed an FGFR1 mutation." (PMID 38903142, 2024).
tumor (continued). "Her tumor tissue was sent for molecular testing and 2 mutations were detected in the FGFR1 and PTPN11 genes." (PMID 38903142, 2024). "Alterations in FGFR1–3, including fusions, amplifications, and mutations, have been observed across tumor types and have formed the basis of basket trials." (PMID 38938274, 2024). "Both samples had a shared truncal GATA3M400fs mutation and a shared FGFR1 high amplification, which was additionally classified as a focal high amplification for the tumor sample." (PMID 38503755, 2024). "The tumor tissue was also positive for well-characterized activating alterations in FGFR1 p.Asn546Lys and two variants in PIK3CA p.His1047Arg and p.His1047Tyr." (PMID 39309743, 2024). "More importantly, many of the downregulated genes (Fn1, Hspb1, Postn, Mia, Fgfr1, Serpine2) have been associated with tumor metastasis." (PMID 39287984, 2024). "Specifically, FGFR1 mutations are key drivers of tumor development and have been widely observed across different RGNT cases." (PMID 39457636, 2024). "RGNTs in the midbrain tegmentum, which show greater cellular heterogeneity, often carry mutations in the FGFR1 gene, and are linked to increased tumor cell proliferation and invasiveness." (PMID 39457636, 2024). "Twenty‐eight validation cohort tumours that had been classified by radiology possessed a consensus clustering classification or detectable BRAF/FGFR1 variant." (PMID 36843390, 2023). "Next, as a second prototypical example, we conducted tests on FGFR1, another promising druggable target associated with tumor progression and invasion." (PMID 37989998, 2023). "Associations between patient and tumor characteristics and FGFR1 expression in tumor-adjacent and tumor tissues." (PMID 37546410, 2023). "High FGFR1 expression in tumor tissues is associated with less favorable tumor characteristics, and FGF ligand (FGF1, FGF11, FGF18) expression is associated with MBD." (PMID 37546410, 2023). "Our findings further show an association between high tumor-specific FGFR1 levels with histological grade 3, high Ki67 index and Luminal B-like tumors." (PMID 37546410, 2023). "Much like FGFR gene fusions, FGFR1 ITD positive tumours are thought to be less aggressive than FGFR mutated tumours." (PMID 37130917, 2023). "Exogenous recombinant IGFBP7 treatment in macrophages and GC cells further identified that IGFBP7 promotes tumor associated macrophage (TAM) polarization via FGF2/FGFR1/PI3K/AKT axis." (PMID 36681667, 2023). "FGFR1 gene amplification was associated with late tumor stages, and in female patients this alteration was linked to better overall survival." (PMID 37445817, 2023). "In humans, high tumor levels of phosphorylated FGFR1 associated with a shorted disease-free survival after tamoxifen treatment and with an elevated BMI." (PMID 37800138, 2023). "In this former study, it was shown that FGFR1 amplification was linked to better overall survival in female patients and to late tumor stages in LSCC." (PMID 37445817, 2023). "Here we report a novel circular RNA, circFGFR1int2, derived from intron 2 of FGFR1 gene, which is overexpressed in PCa and associated with tumor progression." (PMID 37993879, 2023). "To better study the role of these co-driver alterations, we assembled a large paediatric and adult cohort of 29 tumours H3K27-altered with co-occurring activating mutation in BRAF or FGFR1 as well as 31 previous cases from the literature." (PMID 38066305, 2023). "Second, BRAF and FGFR1 mutations were mutually exclusive, as only one tumour presented both hits (case #23)." (PMID 38066305, 2023).
tumor (continued). "For example, recurrent amplification of oncogenes such as MYC, ERBB2 (HER2), and FGFR1, and significant loss of tumor suppressors such as CDKN2A and CDKN2B were observed in the high-CRRS group." (PMID 36936912, 2023). "Recently, FGFR1 alterations have been shown to be associated with worse prognosis compared to FGFR1 NMD in patients with PIK3CAmut tumours treated with ET." (PMID 36892268, 2023). "For instance, tumour cells harbouring activating V561M mutation in the FGFR1 kinase domain showed resistance to both specific inhibitors AZD4547 and infigratinib; and non-specific inhibitors, such as ponatinib, TKI258, and lucitanib (E3810)." (PMID 36497187, 2022). "The 8p11 myeloproliferative syndrome (EMS) is an aggressive neoplasm associated with chromosomal translocations involving the fibroblast growth factor receptor 1 tyrosine kinase gene on chromosome 8p11." (PMID 35386486, 2022). "Among the progressive specific DNTs, 17 tumours (68%) harboured an FGFR1 disruption, including 10 ITDs, 5 mutations, 1 fusion and 1 other alternative SV." (PMID 35836307, 2022). "In one case, tissue of the recurring tumor was available and the identical FGFR1 hotspot mutation was detected." (PMID 35018490, 2022). "The NGS cancer‐hotspot analysis on tumor DNA revealed a c.1632C>A, p.(Asn544Lys) pathogenic variant of the FGFR1 gene (NM_001174063.2) with a VAF of 36%, confirmed by Sanger sequencing." (PMID 35778969, 2022). "Mutations or structural variations (SVs) involving FGFR1 were found in 37/51 of the DNA methylation profiled tumours (73%), including 23 ITDs, 9 mutations, 2 fusions and 3 other SVs." (PMID 35836307, 2022). "Oversignaling through this cascade is therefore enhanced by both the PTPN11 and the FGFR1 variant, likely representing two hits in the tumor progression." (PMID 35778969, 2022). "We next investigated the underlying mechanism by which the tumor cell–derived FGFBP1-triggered activation of the FGF2/FGFR1 axis induced FAPα expression in HSCs." (PMID 35951441, 2022). "Further, we showed that loss of 4EBP1 enhanced tumor growth of FGFR1-4EBP1-amplified cancer cells and reduced their sensitivity to FGFR1 and PI3K inhibition." (PMID 35626002, 2022). "A pathogenic variant in FGFR1 was also found in tumor tissue, representing a second hit on the RAS/MAPK pathway." (PMID 35778969, 2022). "We found several, potentially clinically relevant, tumor-specific associations between FGFR1-4 genomic alterations and other genomic markers." (PMID 36462464, 2022). "Our study in patients overexpressing the HER2 gene (HER2-positive) shows that FGFR1 gene amplification is associated with a poor tumor response to both anti-HER2 treatments, trastuzumab and trastuzumab plus pertuzumab." (PMID 35213975, 2022). "It has been shown that tumours coamplified for FGFR1 and CCND1 are associated with an especially poor prognosis." (PMID 35459982, 2022). "In the literature, FGFR1 mutation has been reported in only one tumour diagnosed as DLGNT, but this diagnosis was doubtful because of the presence of a H3K27M mutation, the lack of 1p status information, and the absence of DNA methylation profiling." (PMID 36264505, 2022). "We have very recently demonstrated that FGFR1 hotspot mutations are also frequently seen in other low-grade tumor entities." (PMID 35455503, 2022). "Here, a pathway is described in which the fibroblast growth factor receptor 1 (FGFR1) activated by FGF1-derived from cancer-associated fibroblasts (CAFs) is augmenting the tumor cell intrinsic MYC signal." (PMID 34637026, 2021). "Expression changes in different member molecules of this pathway are associated with tumor progression (FGFR1 and 4) and loss of tissue differentiation, and aggressiveness." (PMID 34956100, 2021). "In this context, FGFR1 MU status was significantly associated with a better overall survival, independently of patient age, and tumor localization (p = 0.026)." (PMID 33433639, 2021).
tumor (continued). "Higher age (≥ 18 years), supratentorial tumor localization and FGFR1 MU status were associated with a significantly better prognosis of patients (p = 0.038, p = 0.034, and p = 0.023, online resource)." (PMID 33433639, 2021). "We noted complete loss of FGFR1 expression in tumors treated with FGFR1i-AuNSs, extracted from the center of the specimen; thus, indicating a high tumor penetration and enhanced drug delivery to cancer cells." (PMID 33596850, 2021). "Subsequently, cfDNA was evaluated by two approaches, i.e., mFAST-SeqS and shallow whole-genome sequencing (sWGS), to estimate the circulating tumor DNA (ctDNA) allele fraction (AF) and to evaluate the FGFR1 status." (PMID 32517171, 2020). "The remaining three tumors had high tumor content based on FGFR1 mutant allele frequencies of > 25%, indicating that the reason for failure to closely cluster was due to other causes." (PMID 32859279, 2020). "In estrogen-free conditions, FGFR1 was associated with ER in tumor cell nuclei and regulated the transcription of ER-dependent genes." (PMID 33081025, 2020). "This tumor harbored both an FGFR1 in frame insertion and a PIK3CA E454K mutation detected by RNA sequencing." (PMID 31677015, 2020). "First is that the relative tumor content of these samples is low, which was the case for two of the five tumors (uLGNET #3 and #4) based on the low FGFR1 mutant allele frequencies of 10% and 6%, respectively." (PMID 32859279, 2020). "Associations between specific FGFR1 alteration, accompanying genetic alteration(s), tumor histology, and epigenetic signature are described in detail below." (PMID 32859279, 2020). "In a phase I trial combination therapies of FGFR and PI3K inhibitors (infigratinib/BYL719) were tested in tumours with PIK3CA mutations or genetic alterations in FGFR1-3." (PMID 35582593, 2019). "We also found evidence of an association of activated FGFR1 when localized in the cell membrane with malignancy and tumor grade (2 and 3)." (PMID 30931252, 2019). "Next generation sequencing of circulating tumor DNA (ctDNA) in 34 patients after progression on CDK4/6 inhibitors identified FGFR1/2 amplification or activating mutations in 14/34 (41%) post-progression specimens." (PMID 30914635, 2019). "The loss of the homeostasis-promoting intrinsic FGFR2 signaling and concurrent gain of ectopic FGFR1 expression in epithelial tissues of a variety of organs are found associated with tumor progression." (PMID 30761180, 2019). "TMA results for FGFR1 expression reveal associations of FGFR1 expression levels with age, tumor location and malignancy." (PMID 30931252, 2019). "Overexpression of FGFR1 was significantly associated with both low tumor grade (P = 0.023) and low tumor stage (P = 0.023)." (PMID 30593273, 2018). "Using genetic tools in the mouse, we examine the effects of in vivo cell-autonomous Vegfr2 heterozygosity, alone and in combination with endothelial Fgfr1/2 loss, on tumor angiogenesis and growth." (PMID 30283071, 2018). "While this cohort is small, these data and TCGA suggest that FGFR1 methylation is potentially associated with its re-expression in HNSCC tumor samples in response to cetuximab treatment." (PMID 29792227, 2018). "Subsequently, further study shows that high expression of FGFR1 is associated with tumor progression and survival in diffuse-type gastric cancer, but not in intestinal-type gastric cancer." (PMID 30484492, 2018). "Both MUG-Myx2 cell lines showed a similar pattern of CNVs in these genes and shared the distinct loss of CDKN2a and MLH1, as well as a gain of FGFR1, with the primary tumor tissue." (PMID 28304377, 2017).